TRIM26 (tripartite motif containing 26)
Diseases named in the same sentence as TRIM26 in open-access papers (continued):
Sharing a sentence is not in itself a finding about the gene and the disease.
osteosarcoma (2 papers, 2023 to 2025). A usually aggressive malignant bone-forming mesenchymal neoplasm, predominantly affecting adolescents and young adults. "Lower expression of TRIM26 was associated with worse overall survival in patients with osteosarcoma." (PMID 37591850, 2023). "Survival analysis revealed that higher expression of TRIM26 was associated with better prognosis and its expression was an independent protective factor in osteosarcoma." (PMID 37591850, 2023). "This study revealed a novel role of the TRIM26/RACK1 axis in osteosarcoma progression and the underlying mechanism." (PMID 37591850, 2023). "In our previous studies, TRIM26 was associated with osteosarcoma progression." (PMID 41145484, 2025). "Additionally, Kaplan–Meier survival analysis illustrated that higher expression of TRIM26 was associated with a better prognosis in patients with osteosarcoma." (PMID 37591850, 2023). "As the mechanism of TRIM26 in osteosarcoma has been previously investigated, this study focuses on exploring the role of TRIM17 in osteosarcoma." (PMID 41145484, 2025). "Our results suggested that TRIM26 overexpression dramatically inhibited the proliferation of osteosarcoma cells, and reduced cellular invasion." (PMID 37591850, 2023). "The CCK-8 and colony formation assays were further carried out and confirmed that the silence of TRIM26 significantly inhibited cell proliferation in osteosarcoma cells." (PMID 37591850, 2023). "Functional analysis demonstrated that overexpression of TRIM26 inhibited osteosarcoma cell proliferation and invasion via inhibiting the EMT process and MEK/ERK signaling." (PMID 37591850, 2023). "Mechanistically, our results suggested that TRIM26 inhibited osteosarcoma progression via accelerating the degradation of RACK1, and thus resulted in the inactivation of MEK/ERK signaling and impeded the EMT process." (PMID 37591850, 2023). "In conclusion, our study indicated that TRIM26 inhibited osteosarcoma progression via promoting proteasomal degradation of RACK1, thereby resulting in inactivation of MEK/ERK signaling, and impeding the EMT process." (PMID 37591850, 2023). "Then, we explored the influence of silencing and overexpressing TRIM26 on RACK1 expression in osteosarcoma cells." (PMID 37591850, 2023). "We found that overexpression of TRIM26 increased the ubiquitination of RACK1, whereas depletion of TRIM26 significantly decreased RACK1 ubiquitination in osteosarcoma cells." (PMID 37591850, 2023). "To explore the potential molecular mechanism underpinning TRIM26-mediated inhibition of osteosarcoma cell proliferation and invasion, we performed RNA-Seq after TRIM26 overexpression in biological duplicates in 143B cells." (PMID 37591850, 2023). "In this study, we found that TRIM26 was a protective factor in osteosarcoma and that its lower expression predicted a worse clinical outcome, indicating a tumor-suppressive role for TRIM26 in osteosarcoma." (PMID 37591850, 2023). "To gain insights into the role of TRIM26 in osteosarcoma, we upregulated its expression through lentiviral infection." (PMID 37591850, 2023). "Univariate and multivariate Cox regression analyses indicated that TRIM26 was a protective factor and an independent prognostic biomarker in osteosarcoma." (PMID 37591850, 2023). "We further investigated the role of RACK1 in the mechanism by which TRIM26 inhibits the progression of osteosarcoma." (PMID 37591850, 2023). "To explore the functional role of TRIM26 in osteosarcoma, we first analyzed TRIM26 expression in different tumors represented in the TCGA database." (PMID 37591850, 2023). "The transwell invasion assay revealed that silencing TRIM26 significantly enhanced the invasiveness of osteosarcoma cells." (PMID 37591850, 2023). "To further explore the role of TRIM26 on osteosarcoma cell proliferation and invasion, we silenced its expression by lentivirus-mediated transfection of shTRIM26." (PMID 37591850, 2023).
osteosarcoma (continued). "Collectively, these results suggest that TRIM26 was a potential prognostic predictor and a promising therapeutic target for treating osteosarcoma." (PMID 37591850, 2023). "In this study, we found that TRIM26 was downregulated in osteosarcoma, and its expression was an independent protective factor and correlated with a better prognosis in osteosarcoma patients." (PMID 37591850, 2023). "Western blot and qRT-PCR analyses suggested that mRNA and protein levels of TRIM26 were significantly lower in osteosarcoma tissue samples compared to adjacent normal." (PMID 37591850, 2023). "TRIM26 inhibited osteosarcoma progression via promoting the degradation of RACK1, and thus inactivation of the MEK/ERK pathway." (PMID 37591850, 2023). "Subsequently, we manipulated TRIM26 expression in osteosarcoma cells and performed functional experiments." (PMID 37591850, 2023). "Little is known about TRIM26 in osteosarcoma, so we measured its expression in osteosarcoma tissue samples and cell lines." (PMID 37591850, 2023). "Herein, we found that TRIM26 was markedly downregulated in osteosarcoma tissues and cells." (PMID 37591850, 2023). "In the future, TRIM26 might be served as a candidate prognostic biomarker and a potential target for new therapies in osteosarcoma." (PMID 37591850, 2023). "Moreover, TRIM26 expression was significantly reduced in osteosarcoma cells (143B, U2OS, MG63, and HOS) compared with normal osteoblasts (hFOB1.19)." (PMID 37591850, 2023). "Moreover, we manipulated the expression of RACK1 in TRIM26-upregulated or TRIM26-silenced osteosarcoma cells through plasmid or siRNA transfection." (PMID 37591850, 2023). "In conclusion, our study provided evidence of the tumor-suppressive role of TRIM26 in osteosarcoma." (PMID 37591850, 2023). "Moreover, analyzing its expression in osteosarcoma cells and tumor tissues suggested that TRIM26 expression was dramatically lower in osteosarcoma tissues and cell lines compared with normal." (PMID 37591850, 2023). "In addition, overexpression of TRIM26 markedly inhibited tumor growth in the xenografts mouse model, further supporting the tumor-suppressive role of TRIM26 in osteosarcoma." (PMID 37591850, 2023). "TRIM26 might be a potential prognostic predictor and a promising therapeutic target for treating osteosarcoma." (PMID 37591850, 2023). "TRIM26, one of the TRIMs family genes, was more frequently reported to exert a tumor-suppressive role, while its detailed functional roles in the osteosarcoma progression were still unknown and require further investigation." (PMID 37591850, 2023). "Therefore, we could conclude that TRIM26 inhibits cell proliferation and invasion in osteosarcoma through destabilizing RACK1 and thus inactivation of MEK/ERK signaling." (PMID 37591850, 2023). "However, the specific functional role of TRIM26 in osteosarcoma and its underlying mechanism has not been sufficiently elucidated." (PMID 37591850, 2023). "Thus, we could conclude that TRIM26 inhibited osteosarcoma proliferation and invasion via inactivation of MEK/ERK signaling." (PMID 37591850, 2023). "Venn diagram analysis of the survival and differential expression results demonstrated that TRIM26 and TRIM17 were differentially expressed in osteosarcoma and correlated with patient prognosis." (PMID 41145484, 2025). "Taken together, these results suggest that overexpression of TRIM26 inhibits tumor growth by destabilizing RACK1 and thus inactivation of MEK/ERK signaling in osteosarcoma." (PMID 37591850, 2023). "Taken together, these results suggest that TRIM26 inhibits cell proliferation and invasion by inhibiting EMT in osteosarcoma." (PMID 37591850, 2023). "Immunoprecipitation assay in 143B cells suggested that RACK1 was precipitated by TRIM26 and reverse immunoprecipitation confirmed that TRIM26 could also be precipitated by RACK1 in osteosarcoma cells." (PMID 37591850, 2023).
acute kidney injury (1 paper, 2024). Sudden and sustained deterioration of the kidney function characterized by decreased glomerular filtration rate, increased serum creatinine or oliguria. "Furthermore, Trim26–/–kidneys showed significantly up-regulated expression of kidney injury molecule-1 (KIM-1) and neutrophil gelatinase-associated lipocalin (NGAL), markers of tubular epithelial damage used for the early diagnosis of acute kidney injury (AKI)." (PMID 38166150, 2024).
asthma (1 paper, 2024). "Cluster 5, which includes genes at 6p22.1 (HLA-A, HCG4P5, HLA-T, MOG, TRIM26, HCG9, IFITM4P), demonstrated further connections between JIA and a subset of autoimmune/inflammatory traits (i.e., type 1 diabetes, asthma, eczema, and severe COVID-19 or rheumatoid arthritis)." (PMID 39175752, 2024).
candidiasis (1 paper, 2024). Infection with the organism Candida. "Collectively, these data suggested that Trim26 deficiency promotes the upregulation of inflammatory gene expression in kidney-infiltrated neutrophils during candidiasis." (PMID 38166150, 2024). "We found Trim26-deficient mice exhibit increased recruitment of neutrophils into the kidneys during the process of Candida infection (1–7 days post-infection)." (PMID 38166150, 2024). "Overall, our study elucidated the mechanisms by which Trim26 regulates inflammatory neutrophil infiltration and plays a protective role by alleviating renal injury during candidiasis." (PMID 38166150, 2024). "In summary, we demonstrated the crucial role of Trim26 in antifungal responses by restricting inflammatory neutrophils infiltration and limiting proinflammatory cytokines production in the kidneys during Candida infections." (PMID 38166150, 2024). "Mechanistically, Trim26 restricts inflammatory neutrophils infiltration and limits proinflammatory cytokine production, which can attenuate kidney fungal load and renal damage during Candida infection." (PMID 38166150, 2024). "In the present study, we found that Trim26 attenuates renal damage by restricting inflammatory neutrophil infiltration and limiting the production of proinflammatory cytokines in the kidney during Candida infection." (PMID 38166150, 2024). "Together, our study findings unraveled the vital role of Trim26 in regulating antifungal immunity through the regulation of inflammatory neutrophils infiltration and proinflammatory cytokine and chemokine expression during candidiasis." (PMID 38166150, 2024). "Indeed, using the in vivo model of invasive candidiasis, we found that reparixin administration at three consecutive doses at 2, 4, and 6 days after C. albicans infection resulted in significantly prolonged survival of Trim26–/–mice compared with treatment with the diluent alone." (PMID 38166150, 2024).
colitis (1 paper, 2021). Inflammation of the colon. "In addition, TRIM26-mediated K11-linked TAB1 polyubiquitination has been found to enhance TAK1 activation and subsequent activation of NF-κB and MAPK signaling pathways in macrophages, pointing to a pro-inflammatory role of TRIM26 in DSS-induced colitis." (PMID 34956195, 2021).
colon adenocarcinoma (1 paper, 2024). "Our TCGA database analysis of the Trim26 gene expression as shown in RNA-sequencing data from TNMplot.com showed that its RNA level is significantly higher in colon adenocarcinoma tissues than that in healthy colon tissues." (PMID 38260302, 2024).
epilepsy (1 paper, 2021). A brain disorder characterized by episodes of abnormally increased neuronal discharge resulting in transient episodes of sensory or motor neurological dysfunction, or psychic dysfunction. "Bioinformatics analysis revealed that the effects of AS3MT on epilepsy likely involved multiple targets including MTHFR, GSTM1, CYP17A1, NT5C2, YBX3, CNNM2, CACNB2, and TRIM26." (PMID 34899152, 2021). "The effects of AS3MT on epilepsy might involve multiple targets including CNNM2, CACNB2, TRIM26, MTHFR, GSTM1, CYP17A1, NT5C2, and YBX3." (PMID 34899152, 2021).
fungal infection (1 paper, 2024). "This may explain the increased expression of the proinflammatory cytokine Trim26–/–kidneys after fungal infection." (PMID 38166150, 2024). "Herein, we report that Trim26 exerts protective antifungal immune functions after fungal infection." (PMID 38166150, 2024). "We found that Th1 and Th17 levels were not markedly changed in the lymph nodes and spleen of Trim26-deficient mice compared with those in control mice after fungal infection." (PMID 38166150, 2024).
glucose metabolic disorder (1 paper, 2023). "Hepatocyte-specific loss of Trim26 disrupts liver metabolic homeostasis, followed by glucose metabolic disorder, lipid accumulation, increased hepatic inflammation, and fibrosis, and dramatically facilitates NASH-related phenotype progression." (PMID 37821436, 2023).
kidney cancer (1 paper, 2025). Primary or metastatic malignant neoplasm involving the kidney. "TRIM7, TRIM13, and TRIM26 regulate the PI3K/AKT/mTOR pathway as tumor suppressors in kidney cancers." (PMID 40723250, 2025).
kidney damage (1 paper, 2024). "Further investigation showed that the excessive neutrophils infiltration and higher proinflammatory cytokines and chemokines production, which cause kidney damage, contributed to the higher mortality rate of Trim26-deficienet mice." (PMID 38166150, 2024).
leukemia (1 paper, 2022). A malignant (clonal) hematologic disorder, involving hematopoietic stem cells and characterized by the presence of primitive or atypical myeloid or lymphoid cells in the bone marrow and the blood. "The roles of the top-ranking gene Trim26 in HSCs and leukemia are unknown." (PMID 35484199, 2022).
liver steatosis (1 paper, 2023). "In a set of mice models exhibiting non-alcoholic steatohepatitis (NASH), the targeted removal of TRIM26 specifically in hepatocytes resulted in a substantial increase in hepatic steatosis, liver inflammation, and hepatofibrosis." (PMID 37821436, 2023). "It was shown that following a prolonged challenge of a HFHC or WTDF diet, the ablation of Trim26 in hepatocytes resulted in a significant increase in liver steatosis, hepatic inflammation, and hepatofibrosis." (PMID 37821436, 2023). "Besides, Trim26 ablation did slightly elevate Cebpd-Hif1a signalling and its corresponding downstream pathways, including Cebpd, Hif1a, Nos2, p-p38, and p-p65 protein, in HFHC- and WTDF-induced fatty liver and NASH serum-treated AdTRIM26- or AdshTRIM26-transfected L02 cells." (PMID 37821436, 2023).
medulloblastoma (1 paper, 2021). A malignant, invasive embryonal neoplasm arising from the cerebellum. "TRIM26 was also identified in a discovery set of SOX2-interacting proteins in a medulloblastoma cell line, but the interaction has not yet been validated or functionally examined." (PMID 34732716, 2021).
metabolic syndrome (1 paper, 2023). A cluster of metabolic risk factors for CARDIOVASCULAR DISEASES and TYPE 2 DIABETES MELLITUS. "The findings of this study provide additional evidence that the fundamental catalytic role of two conserved motifs within the RING domain of TRIM26 could serve as a specific target for inhibiting the development of NASH and its related metabolic syndrome produced by metabolic stress." (PMID 37821436, 2023).
non-alcoholic steatohepatitis (1 paper, 2023). "Therefore, we have established that there is a notable reduction in TRIM26 levels in liver tissues, which exhibits a negative association with the expression of markers indicative of non-alcoholic steatohepatitis (NASH) in both human subjects and a mouse model of NASH." (PMID 37821436, 2023).
prostate carcinoma (1 paper, 2025). A carcinoma that arises from epithelial cells of the prostate gland. "In summary, our results illustrate that evodiamine exerts potent antitumor effects against prostate cancer through promoting TRIM26-mediated degradation of GPX4 protein and triggering ferroptosis." (PMID 40420092, 2025). "IHC and Western blot analyses confirmed that evodiamine induces ferroptosis in prostate cancer cells by decreasing TRIM26 expression, which in turn inhibits the stability of GPX4." (PMID 40420092, 2025). "These in vivo findings suggest that evodiamine can inhibit prostate cancer tumor growth through the TRIM26/GPX4 signaling pathway." (PMID 40420092, 2025). "This study demonstrates that evodiamine exerts potent antitumor effects against prostate cancer through inhibiting TRIM26-mediated stabilization of GPX4 protein and triggering ferroptosis." (PMID 40420092, 2025). "To gain deeper insights into the role of TRIM26, we overexpressed it in prostate cancer cells and subsequently evaluated its influence on evodiamine-induced inhibition of GPX4 protein expression." (PMID 40420092, 2025). "Given that evodiamine can induce ferroptosis in prostate cancer cells in vitro through the TRIM26/GPX4 signaling axis, we evaluated its effects on prostate cancer tumor growth in vivo." (PMID 40420092, 2025).
Sepsis (1 paper, 2025). Sepsis is defined as life-threatening organ dysfunction caused by a dysregulated host response to infection. "Therefore, TRIM26 protects mice from LPS-induced sepsis via ubiquitination." (PMID 40918153, 2025). "Here, this study aims to investigate the potential mechanism of ET in reducing inflammation in sepsis based on macrophage autophagy and reveal whether ET restores the autophagic flux in macrophages, inhibit NLRP3 inflammasome activation in septic mice through the regulation of TRIM26." (PMID 40918153, 2025).
steatosis (1 paper, 2023). Increased lipid within the cytoplasm of cells. "The lower graph of human patients’ spearman correlation analysis was to determine the correlation between non-steatosis, simple steatosis, and NASH groups based on TRIM26 expression abundance." (PMID 37821436, 2023).
toxoplasmosis (1 paper, 2026). A parasitic disease contracted by the ingestion or fetal transmission of toxoplasma gondii. "Additionally, it elucidates the significance of TRIM26 in the host immune response to T. gondii, and providing new insights and potential targets for the prevention and treatment of toxoplasmosis." (PMID 41652078, 2026).
ZIKV infection (1 paper, 2022). "As such, the biological relevance of capsid interaction with TRIM26 during ZIKV infection is not clear." (PMID 35632712, 2022).